RNU6-927P (RNA, U6 small nuclear 927, pseudogene)
Gene: Small nuclear RNA gene on chromosome 12 (124,901,512 to 124,901,611, forward strand). Ensembl gene ENSG00000252008.
Homologues: Orthologues: macaque U6 (92% identical), chimpanzee U6 (66% identical), mouse Gm25599 (56% identical). Paralogues in human: RNU6-1152P (73% identical), RNU6-166P (72% identical), RNU6-1048P (71% identical), RNU6-1175P (71% identical), RNU6-924P (71% identical), RNU6-1060P (70% identical), RNU6-1155P (70% identical), RNU6-1243P (70% identical), RNU6-19P (70% identical), RNU6-211P (70% identical), RNU6-429P (70% identical), RNU6-589P (70% identical), and 1287 more.